PUM2 (pumilio RNA binding family member 2)
Diseases named in the same sentence as PUM2 in open-access papers (continued):
Sharing a sentence is not in itself a finding about the gene and the disease.
cancer (22 papers, 2008 to 2025). A tumor composed of atypical neoplastic, often pleomorphic cells that invade other tissues. "For example, miRNA‐130a expressed by cancer‐associated fibroblasts derived from TME in cancer was packaged into exosomes by mutual effecting with the RNA‐binding protein PUM2." (PMID 39247621, 2024). "In the TCam-2 seminoma cell line, it has recently been demonstrated that PUM1 and PUM2 regulate several mRNAs functionally linked to cancer." (PMID 33401540, 2021). "PUM2 is involved in multiple cellular responses and disease processes, including cancer development and progression." (PMID 40629911, 2025). "Other studies report lower PUM2 expression in LumA and TNBC tumors compared to normal tissues and that PUM2 silencing increases cell viability, migration and invasion in cancer cells lines, while its OE produces the opposite effect." (PMID 38339387, 2024). "PUM2 proves, yet again, its importance and broad range of targets and its ability to influence cancer-related signaling pathways." (PMID 38339387, 2024). "Pumilio RNA binding family member 2 (PUM2) is a PUF family member of RBPs that modulates malignant tumors." (PMID 37596669, 2023). "KEGG pathway analyses of the changed mRNAs and proteins in Pum1−/− and Pum2−/− HCT116 cells revealed that cancer-related genes were enriched." (PMID 35338151, 2022). "Future experiments are clearly needed to unravel the role of Pum2 in regulating cancer metastasis formation." (PMID 34445704, 2021). "The accumulated data show that the expression levels of PUM1 and PUM2 are significantly altered in 17 types of cancer tissues." (PMID 33401540, 2021). "Among these RBPs, Pum2 mRNA exhibited selective and significant enrichment in cancer cells compared to neural progenitor cells or mature neurons." (PMID 34445704, 2021). "Taking advantage of the Cancer Genome Atlas database, we analyzed RNA expression levels of PUM1 and PUM2 from human cancer samples and compared them to PUM expression in healthy tissues collected within the Genotype-Tissue Expression (GTEx) project." (PMID 33401540, 2021). "We found that the majority of those PUM1- and PUM2-regulated targets are involved in cancer (16 among 19), including 10 in cancer of the male or female reproductive system." (PMID 32316190, 2020). "Human Pumilios, Pumilio1 (PUM1) and Pumilio2 (PUM2), are sequence-specific RBPs whose targets often encode proteins acting in cancer-related pathways." (PMID 31655860, 2020). "Though roles of PUM2 in proliferation of germ cell and stem cell are well documented in the literatures, involvement of PUM2 in cancer growth remains controversial." (PMID 30787206, 2019). "Of the many RBPs that bind to the KRAS 3′ UTR, AGO2, HuR (or ELAVL1), IGF2BP1/2/3, PUM2, EWSR1, TAF15, FUS, and TIA1 have been previously implicated in cancer." (PMID 26930719, 2016). "Furthermore, the human Pum1 and Pum2 genes have been shown to be mis-expressed in various types of cancers, and there is increasing evidence that this misexpression impacts tumorigenesis." (PMID 37747106, 2023). "This review summarizes the dysregulation of PUM1 and PUM2 expression in several cancer tissues." (PMID 33401540, 2021). "Notably, in the majority of cancer tissues, PUM2 RNA expression was considerably higher than PUM1 expression." (PMID 33401540, 2021). "The findings concerning PUM1 and PUM2 mRNA targets and their functional relations in TCam-2 cells are of interest and should be validated in patients suffering from testis germ cell tumors and several types of cancer affecting other human tissues." (PMID 33401540, 2021). "This review describes PUM1 and PUM2 ribonucleoprotein networks and highlights the mechanisms underlying the regulatory role of PUM proteins and, most importantly, the emerging impact of PUM dysregulation in cancer." (PMID 33401540, 2021). "Pum2 has been showed to play a key role in cancer development." (PMID 33999859, 2021).
cancer (continued). "Due to its high expression in cancer cells, it is tempting to speculate that Pum2 is also needed for integration of cancer cells into neuronal circuits." (PMID 34445704, 2021). "Due to the high expression of Pum2 in cancer cells and their great potential to growth and division, we speculated that Pum2 regulates growth in cells." (PMID 34445704, 2021). "We have systematically analyzed the mRNAs associated with the two human Pumilio RNA-binding proteins, PUM1 and PUM2 in HeLa S3 cancer cells, using a method that combines the recovery of endogenous RNP complexes and DNA microarray analysis of the associated mRNAs." (PMID 18776931, 2008). "In addition to nerve cells, Pum2 is highly expressed in different cancer cells." (PMID 34445704, 2021). "Moreover, it is tempting to speculate that it also contributes to growth and proliferation of cancer cells identifying Pum2 as novel oncotarget for therapies." (PMID 34445704, 2021). "Furthermore, the exact cellular pathways targeted by PUM2 in cancer cells remain unexplored." (PMID 30787206, 2019). "However, roles of PUM2 in cancer development are controversial." (PMID 30787206, 2019). "Consistent with tumorigenic defects in Pum1−/− and Pum2−/− HCT116 cells, PUM proteins appear to regulate the expression of cancer-related genes to promote CRC growth." (PMID 35338151, 2022). "Abnormal profiles of PUM expression have been shown in several types of cancer, in some of them being different for PUM1 and PUM2." (PMID 33401540, 2021). "Consequently, it is tempting to speculate that Pum2 may promote cancer growth." (PMID 34445704, 2021). "Here, we focus on the positive cell cycle regulator PUM2 and its potential target BTG1 which inhibits cancer cell proliferation and promotes apoptosis." (PMID 30787206, 2019). "To identify mRNAs associated with human PUM proteins, we used a modified Ribonucleoprotein-ImmunoPrecipitation Microarray (RIP-Chip) approach on HeLa S3 cancer cells that express both PUM1 and PUM2." (PMID 18776931, 2008). "Additionally, we analyzed the top 100 genes coexpressed with SELENOI across 33 cancer types using GEPIA2.0, and identified PUM2, STRN, WDR43, PRPF40A, and SPAST as highly correlated with SELENOI." (PMID 39669976, 2024). "In contrast, Rbfox1, FMRP, and Stau2 were either not enriched in cancer cells or showed reduced expression compared to Pum2." (PMID 34445704, 2021). "Testicular cancers are the most frequently diagnosed malignant tumors in young Caucasian males, and their incidence has increased, highlighting the importance of the human male germ cell context in studying PUM1- and PUM2-controlled regulation." (PMID 32316190, 2020). "Marvelously, PUM2 and TUG1 involved with cell cycle regulation showed significant positive expression correlation (p < 0.05) in all 14 cancer types." (PMID 25642422, 2014). "Moreover, we compared cancer cell expression with mRNA levels in healthy neural progenitor cells and mature neurons for essential neuronal RBPs such as FMRP, RNA-binding protein fox-1 (Rbfox1), Staufen2 (Stau2), and Pum2." (PMID 34445704, 2021). "In this type of cancer, even though the level of PUM1 or PUM2 protein itself did not change significantly, the level of the miRNAs (miR-503, miR125b) synergizing with PUM proteins was decreased significantly, which allowed oncogenesis." (PMID 35338151, 2022).
tumor (16 papers, 2018 to 2025). "At the level of competitive RNA interactions, PUM2 functions as a tumor suppressor by competing with pro-oncogenic miRNAs miR-590-3p/miR-9 for binding at the 3’ UTR of STARD13 mRNA." (PMID 41019082, 2025). "In contrast, injection of nanoparticles loaded with anti-Pum1 siRNA (siPum1@MSN) or anti-Pum2 siRNA (siPum2@MSN) dramatically inhibited tumor growth." (PMID 35338151, 2022). "Overexpression of PUM2 can inhibit the tumor progression by competitively binding to the 3′UTR of STARD13 with miR‐590‐3p and miR‐925." (PMID 32997416, 2020). "PUM2 also plays a significant role in maintaining the identity of stem cells and tumor progression by negatively regulating mitogen-activated protein kinase (MAPK)." (PMID 32670859, 2020). "The xenograft tumor growth in a nude mice was significantly inhibited by the silencing of SCAMP1-TV2 in combination with the overexpression of PUM2." (PMID 32670859, 2020). "Our results are consistent with the previously reported findings that demonstrate PUM2 reduces the stability of DUSP6 mRNA in tumor cells." (PMID 30787206, 2019). "This interaction blocks miRNA-mediated degradation, preserving PUM2’s function as a tumor suppressor and consequently inhibiting cell proliferation, migration, and maintenance of stemness characteristics, underscoring RBPs’ value as regulatory hubs or “molecular switches”." (PMID 41019082, 2025). "Furthermore, tumour xenografts in nude mice with OVCAR3 cells revealed that PUM2 knockdown suppressed tumour growth in vivo." (PMID 40629911, 2025). "As a tumor suppressor, PUM2 is typically attenuated in OS tissue." (PMID 37426488, 2023). "According to some studies, the function of PUM2 is dependent upon tumor type." (PMID 32670859, 2020). "In addition, knockdown of BTG1 reverses effects of PUM2 knockdown on tumor cell proliferation and migration." (PMID 30787206, 2019). "We found a total of 16 RBPs that could match to lncRNA-n326322, including RBMY1A1, EIF4B, and Pum2, which have been reported to have an important influence on tumor progression." (PMID 29416735, 2018). "Therefore, PUM2, by repressing those mRNAs, may be involved in the control of stem cell fate as well as in tumor progression." (PMID 33401540, 2021). "Additionally, based on studies of the PUM cofactors—the NANOS family—it was demonstrated that only NANOS3 protein, and not NANOS1 or NANOS2, cooperates with PUM2 in repression of mRNA encoding the SIAH1 tumor suppressor." (PMID 33401540, 2021). "Western blotting revealed significant upregulation of PUM2, METTL3, and IGF2BP2 in tumour tissues compared with normal controls." (PMID 40629911, 2025). "From the expression level, four RBPs (RBM10, PUM2, QKI2, and TARBP2) were downregulated in tumor tissues compared with normal tissues, while other identified RBPs were consistently upregulated in OS cells." (PMID 37426488, 2023). "PUM-2 presented as a relatively stable tumour, but with a chromosome 13q alteration (leading to gain of mutant CYSLTR2) which also existed in a tumour subclone." (PMID 33588787, 2021). "Notably, transcriptomic data and RTqPCR results demonstrated that while PUM2 and HIF3A were highly expressed in normal tissues, DDB1 showed increased expression in tumor tissues, with CUL1, COPS2, and UBE2D3 remaining unchanged." (PMID 40524221, 2025). "Moreover, it reversed the BC inhibitory effects of PUM2 OE and was accompanied by decreased expression of SASH1, a protein with tumor suppressor activity in TNBC involved in the toll-like receptor 4 (TLR4) signaling pathway." (PMID 38339387, 2024). "In vivo tumor xenograft mice models established by the inoculation of MCF-7 or MDA-MB-231 cell lines with several combinations of SCAMP1-TV2 and PUM2 expression revealed that the simultaneous silencing of SCAMP1-TV2 and PUM2 OE renders the highest inhibition of xenograft tumor growth." (PMID 38339387, 2024).
tumor (continued). "Additionally, PUM2 overexpression combined with knockdown of both UBE2I and CEBPD resulted in the smallest tumor volume among all the groups." (PMID 32997416, 2020). "Transcriptomic data and RT-qPCR findings indicated that PUM2 and HIF3A exhibited high expression levels in normal tissues, while DDB1 showed increased expression in tumor tissues; no significant changes were observed for CUL1, COPS2, and UBE2D3." (PMID 40524221, 2025). "In both 6DT1 and 4T1 cell lines, KD of NANOS1, PUM2, and CPSF4 did not consistently affect primary tumor growth but did significantly reduce the number of metastatic nodules on the lungs compared to shScramble control (shScr)." (PMID 38410477, 2024). "PUM1 itself, but not PUM2, strongly stimulated apoptosis and moderately slowed down cell cycle progression, suggesting that PUM1, similarly to SPIN3, plays the role of a tumor suppressor in TCam-2 cells." (PMID 33401540, 2021).
neurological diseases (2 papers, 2011 to 2023). "Except for PUM2, PIE-Seq was performed here mostly in HEK293FT cells, which may not be the best model for neurological disorders." (PMID 37280234, 2023).
cardiac disease (1 paper, 2019). "Taken together, this indicates an important role for both QKI and PUM2 in fibrotic cardiac disease." (PMID 31284728, 2019).
cardiovascular diseases (1 paper, 2024). "Several lncRNA–mRNA regulatory axes are involved in the action mechanisms of MSC-Exos in cardiovascular diseases, such as KLF3-AS1/sirtuin 1 (SIRT1), MALAT1/autophagy-related 4a (ATG4a), urothelial cancer associated 1 (UCA1)-Bcl-2, and Mir9-3hg/Pum2." (PMID 38812041, 2024).
neurodegenerative disease (1 paper, 2022). A disorder of the central nervous system characterized by gradual and progressive loss of neural tissue and neurologic function. "In contrast to Pum2, TDP-43 deregulation is mainly implicated in neurodegenerative diseases, particularly ALS and FTD, both of which strike layer V neurons in multiple cortical areas late in life." (PMID 35262486, 2022).
psychiatric disorder (1 paper, 2024). A disorder characterized by behavioral and/or psychological abnormalities, often accompanied by physical symptoms. "CLDN-5 expression levels were not related with the duration of psychiatric disorders, but they were negatively correlated with PUM1 levels (spearman r =-0.3831) and positively correlated with PUM2 levels (spearman r = 0.6030)." (PMID 38898501, 2024).
PUM2 also shares sentences with these, for which no sentence is quoted: myeloid leukemia (2 papers); Obesity (2); schizophrenia (2); autism (1); bladder cancer (1); cardiac hypertrophy (1); colon (1); endometrial cancer (1); hepatocellular carcinoma (1); Intellectual disability (1); ischemia reperfusion injury (1); neuroblastoma (1); pancreatic adenocarcinoma (1); pancreatic cancer (1); prostate tumor (1); undifferentiated sarcoma (1).